TBX1 (T-box transcription factor 1)
Description:
Transcription factor that plays a key role in cardiovascular development by promoting pharyngeal arch segmentation during embryonic development (By similarity). Also involved in craniofacial muscle development (By similarity). Together with NKX2-5, acts as a regulator of asymmetric cardiac morphogenesis by promoting expression of PITX2 (By similarity). Acts upstream of TBX1 for the formation of the thymus and parathyroid glands from the third pharyngeal pouch (By similarity). Required for hair follicle stem cell self-renewal (By similarity). Binds to the palindromic T site 5'-TTCACACCTAGGTGTGAA-3' DNA sequence.
Synonyms: CATCH22; CAFS; CTHM; DGCR; DGS; DORV; TBX1C; TGA; VCF; VCFS
Tractability: PROTAC: ubiquitination databases record sites on it.
Gene: Protein-coding gene on chromosome 22 (19,756,703 to 19,783,593, forward strand). Ensembl gene ENSG00000184058.
Subcellular location: Nucleus
Subcellular location (Human Protein Atlas): Cytoplasmic bodies; Nuclear bodies
Pathways (Reactome):
Developmental Biology: Cardiogenesis
Gene Ontology:
Molecular function: DNA-binding transcription factor activity; protein binding; protein homodimerization activity; sequence-specific DNA binding; sequence-specific double-stranded DNA binding; DNA-binding transcription factor activity, RNA polymerase II-specific; RNA polymerase II cis-regulatory region sequence-specific DNA binding
Biological process: embryonic viscerocranium morphogenesis; heart development; parathyroid gland development; pharyngeal system development; soft palate development; thymus development; angiogenesis; anterior/posterior pattern specification; aorta morphogenesis; artery morphogenesis; blood vessel development; blood vessel morphogenesis; cell fate specification; cell population proliferation; cellular response to fibroblast growth factor stimulus; cellular response to retinoic acid; cochlea morphogenesis; coronary artery morphogenesis; determination of left/right symmetry; ear morphogenesis; embryonic cranial skeleton morphogenesis; enamel mineralization; epithelial cell differentiation; face morphogenesis; heart morphogenesis; and 37 more
Cellular component: chromatin; nucleus
Genetic constraint (gnomAD): Loss-of-function variants: 13 observed, 29.42 expected, observed/expected ratio (o/e) 0.44, 90% interval 0.29 to 0.7. The synonymous counts are far from expectation, so gnomAD's model fits this gene poorly and the ratio says little. Missense variants: 535 observed, 462.64 expected, observed/expected ratio (o/e) 1.16, 90% interval 1.08 to 1.24. Synonymous variants: 295 observed, 201.21 expected, observed/expected ratio (o/e) 1.47, 90% interval 1.33 to 1.62.
Homologues: Orthologues: macaque TBX1 (96% identical), pig TBX1 (92% identical), mouse Tbx1 (89% identical), chimpanzee TBX1 (86% identical), rat Tbx1 (86% identical), dog TBX1 (73% identical), tropical clawed frog tbx1 (69% identical), guinea pig TBX1 (68% identical), zebrafish tbx1 (68% identical), Drosophila melanogaster mid (28% identical), Drosophila melanogaster H15 (26% identical), Drosophila melanogaster ocm (26% identical), and 8 more. Paralogues in human: TBX10 (45% identical), TBX2 (34% identical), TBX3 (33% identical), TBX15 (30% identical), TBX20 (30% identical), MGA (29% identical), TBX18 (29% identical), TBX4 (28% identical), TBX5 (28% identical), TBX22 (28% identical), TBX6 (27% identical), TBR1 (26% identical), and 4 more.
Diseases named in the same sentence as TBX1 in open-access papers:
TBX1 is named in the same sentence as 179 diseases in open-access papers, as found by Europe PMC text mining. Sharing a sentence is not in itself a finding about the gene and the disease. The quoted sentences say what the papers report.
DiGeorge syndrome (154 papers, 2009 to 2026). "TBX1 is strongly linked to 22q11.2 deletion syndrome (DiGeorge syndrome), which includes conotruncal heart defects; TBX1 is also expressed in the pharyngeal endoderm, mesoderm and ectoderm." (PMID 40917916, 2025). "Patient-derived iPSCs carrying congenital heart disease–associated mutations, including TBX1 haploinsufficiency as seen in DiGeorge syndrome, have been used to generate cardiac organoids capable of modeling aspects of disease-relevant phenotypes." (PMID 41049289, 2025). "DiGeorge syndrome, commonly caused by 22q11.2 deletions affecting TBX1, exemplifies how disrupted CNCCs migration can impair pharyngeal arch development, leading to mandibular hypoplasia, cleft palate, and cardiovascular defects." (PMID 40988739, 2025). "The TBX1 gene plays a critical role in the development of 22q11.2 deletion syndrome (22q11.2DS), a complex genetic disorder associated with various phenotypic manifestations." (PMID 38905172, 2024). "Screening for differentially regulated genes between Homo sapiens and extinct relatives revealed 13 candidate genes associated with basicranial development, with TBX1, implicated in DiGeorge syndrome, playing a pivotal role." (PMID 38608674, 2024). "In this patient, we found a pathogenic deletion in the DiGeorge syndrome chromosome region 22q11.2 (TBX1 gene included)." (PMID 38586466, 2024). "The 22q11.2 deletion syndrome (22qDS; also known as DiGeorge’s syndrome) is caused by a 2.5-Mb hemizygous deletion of approximately 46 protein-coding genes on chromosome 22, including the Tbx1 gene." (PMID 36676170, 2023). "LOF mutations in TBX1 or TBX5 result in the dramatic cardiovascular phenotypes seen in 22q11.2 deletion syndrome and Holt-Oram syndrome, respectively." (PMID 38205435, 2023). "T-box transcription factor 1 (TBX1) is the main genetic determinant of 22q11.2 deletion syndrome (22q11.2DS), which is a common cause of CHD." (PMID 35035663, 2022). "TBX1 mutations associated with 22q11 deletions and DiGeorge or velocardiofacial syndrome correlate with PDA." (PMID 34350653, 2022). "TBX1, which encodes a T-box transcription factor, is considered a candidate gene for DiGeorge syndrome, velocardiofacial syndrome, and conotruncal anomaly face syndrome." (PMID 36418889, 2022). "Three patients with syndromic SNHI, including one with Usher syndrome (MYO7A variants), one with LEOPARD syndrome (PTPN11 variant), and one with DiGeorge syndrome (TBX1 variant) exhibited unfavorable outcomes with CI." (PMID 36009393, 2022). "In mouse, both loss of Tbx1 and aberrant RA synthesis can result in cardiovascular defects similar to human DiGeorge syndrome patients." (PMID 34643182, 2021). "Loss of Tbx1 function is associated with 22q11 deletion/DiGeorge syndrome phenotypes, including heart defects, craniofacial abnormalities and cleft palates." (PMID 34137816, 2021). "For example, Tbx1 gene mutations are associated with the human DiGeorge syndrome accompanied by a deficiency in hearing function." (PMID 34220452, 2021). "Our aim was to identify new genes where the loss of function caused cardiovascular phenotypes resembling the 22q11.2 deletion syndrome models, that is, heterozygous and homozygous loss of Tbx1." (PMID 34050709, 2021). "In vertebrates, haploinsufficiency for mouse brachyury (Tbx protein) and human TBX3 and TBX1 genes causes dominant phenotypes such as short tails/tailless, Ulnar-Mammary syndrome and DiGeorge syndrome, respectively." (PMID 32986715, 2020). "One particular gene important for PA segmentation is Tbx1, encoding a T-box transcription factor implicated in 22q11.2 deletion syndrome (DiGeorge syndrome [MIM# 188400]; velo-cardio-facial syndrome [MIM# 192430])." (PMID 31412026, 2019).
DiGeorge syndrome (continued). "In humans, hemizygous loss of Tbx1 has been suggested to be a major contributor to the cardiovascular/pharyngeal defects in DiGeorge syndrome, with similar phenotypes evident in mouse mutants and the zebrafish van gogh mutant (vgo; caused by tbx1 mutation)." (PMID 31312422, 2019). "Loss of Tbx1 is associated with DiGeorge Syndrome in humans, which is characterized by OFT and craniofacial defects." (PMID 31091225, 2019). "DiGeorge syndrome is a chromosomal micro-deletion syndrome with cardiovascular defects, due to deficiency of the TBX1 gene." (PMID 29956664, 2018). "Haploinsufficiency of TBX1 causes DiGeorge Syndrome, which includes aortic arch patterning defects, conotruncal heart defects, and malformations of the thymus gland, parathyroid gland, and craniofacial structures." (PMID 29538649, 2018). "Contrarily, knocking down Tbx1, a causative gene for DiGeorge syndrome associated with OT defects, negatively affected the proliferation of RFP+ cells, but not GFP+ cells." (PMID 30087351, 2018). "The loss of TBX1 is recognized as being largely responsible for the 22q11.2 deletion syndrome (22q11DS), the most common deletion syndrome, which also has the most extensive symptoms among CTDs." (PMID 28272434, 2017). "Transcription factor TBX1 plays a pivotal role in heart development and has been implicated in 22q11.2 deletion syndrome." (PMID 28272434, 2017). "Typically, TBX1 mutations in humans result in DiGeorge syndrome, which includes parathyroid aplasia." (PMID 26567182, 2016). "Evidence for the role of CHD7 and TBX1, the causative gene of 22q11.2 deletion syndrome, has been shown in the embryonic development of the thymus in animal models." (PMID 26544072, 2015). "Mutations in the TBX1 gene have been associated with major phenotypes in 22q11 deletion syndromes such as DiGeorge syndrome, conotruncal anomaly face syndrome, and velo-cardiofacial syndrome." (PMID 25022354, 2014). "DiGeorge syndrome, commonly associated with heterozygous deletion of a region of chromosome 22 containing the TBX1 gene, is characterized by defects in the facial skeleton, thymus and heart." (PMID 25142463, 2014). "The 22q11.2 deletion syndromes are linked to the loss of TBX1, a gene necessary for normal thymus development." (PMID 23577124, 2013). "One of the better described craniofacial malformations is DiGeorge’s syndrome, which is characterized by parathyroid hypoplasia, thymic hypoplasia, and outflow tract defects of the heart mostly linked to mutations in TBX1." (PMID 24130849, 2013). "Haploinsufficiency for mouse brachyury and human TBX3 and TBX1 genes causes dominant phenotypes such as short tails/tailless, Ulnar-Mammary syndrome and DiGeorge syndrome, respectively." (PMID 24385932, 2013). "More importantly, our results demonstrate a requirement for Nrp1 function in endothelium that when compromised leads to DiGeorge syndrome-like defects through mechanisms distinct to those associated with Tbx1 deficiency." (PMID 22396765, 2012). "Haploinsufficiency for TBX1 is considered to be the key genetic determinant of human DiGeorge syndrome (DGS), which is caused by a heterozygous chromosomal deletion of 22q11.2." (PMID 22844420, 2012). "Mutations or deletions of Tbx1 result in severe craniofacial malformations and muscle anomalies, prominently observed in conditions such as DiGeorge syndrome and velocardiofacial syndrome, underlining its crucial regulatory role during the early stages of facial muscle development." (PMID 40565856, 2025). "Importantly, four patients had dual diagnoses with glucose-6-phosphate dehydrogenase (G6PD) deficiency: X-linked SCID (IL2RG), C6 deficiency (C6), IPEX syndrome (FOXP3), DiGeorge syndrome (TBX1)." (PMID 35757720, 2022).
DiGeorge syndrome (continued). "The loss of a single copy of TBX1 accounts for most of the clinical signs and symptoms of 22q11.2 deletion syndrome, a common genetic disorder that is characterized by multiple congenital anomalies and brain-related clinical problems, some of which likely have vascular origins." (PMID 36216515, 2022). "Interestingly, mice harboring an allele with both Tbx1 and Crkl inactivated recapitulated aspects of the 22q11.2 deletion syndrome phenotype." (PMID 35046931, 2021). "Of these, TBX1 (T-box transcription factor 1) has emerged as a functionally important candidate, as heterozygous mutations in this gene have been found in patients with clinical features resembling 22q11.2 deletion syndrome." (PMID 35046931, 2021). "The zebrafish van gogh (vgo) mutant affects the transcription factor Tbx1, the loss of which presents both heart and craniofacial defects associated with human DiGeorge syndrome as hypothesized due to a perturbed Tbx1–Wnt regulatory axis in the CPF." (PMID 33578943, 2021). "However, since the identification of TBX1 as the main cardiovascular gene linked to DiGeorge syndrome, it has become clear that this is an indirect effect on NCC, as TBX1 is not expressed in NCC, but it influences their migration." (PMID 32987700, 2020). "Athymia was classically associated with DiGeorge Syndrome due to TBX1 gene haploinsufficiency." (PMID 32922396, 2020). "DiGeorge syndrome and velocardiofacial syndrome have traditionally been studied together in the literature, and both are caused by a hemizygous deletion of chromosome 22q11.2 and are also believed to be caused by point mutations on the TBX1 gene." (PMID 31044086, 2019). "Similarly, TBX1, which harbors mutations that cause the same phenotype as 22q11.2 deletion syndrome, is dark by depth in only approximately 30% of gnomAD samples." (PMID 31104630, 2019). "The 22q11.2 deletion syndrome (22q11.2DS; velo-cardio-facial syndrome; DiGeorge syndrome) is a congenital anomaly disorder in which haploinsufficiency of TBX1, encoding a T-box transcription factor, is the major candidate for cardiac outflow tract (OFT) malformations." (PMID 28346476, 2017). "Interestingly, craniofacial abnormalities reminiscent of the Tbx1-linked DiGeorge’s syndrome have been observed in patients with a microdeletion at 17q21-22, leading to TBX2-haploinsufficiency." (PMID 24130849, 2013). "tbx-2(bx59) mutates a conserved histidine residue within the dimerization domain of the T-box to a tyrosine (H145Y; accession CCD69847), and mutations affecting this domain in human TBX1 result in gain-of-function associated with some cases of DiGeorge and velocardiofacial syndromes." (PMID 23595631, 2013). "Clinical features of congenital heart defects in 22q11.2 deletion syndromes are usually associated with the common 3 Mb deletions involving TBX1, while atypical deletions may show variable phenotypes modified by deletion location, size and other factors." (PMID 22487416, 2012). "Tbx1 function in endothelium is required for proper lymphatic vessel development, although lymphatic defects are not generally thought to contribute to or be part of the clinical spectrum associated with DiGeorge syndrome." (PMID 22396765, 2012). "Interestingly, Tbx1 is believed to be the major mutated gene in DiGeorge syndrome, a human hereditary disease leading to mental retardation attributable to vascular malformations; Tbx1 has previously been described to be downstream of Wnt/β-catenin in non-endothelial cells." (PMID 24590145, 2014). "Haploinsufficiency or mutation of TBX1 is largely responsible for the etiology of physical malformations in individuals with velo-cardio-facial/DiGeorge syndrome (VCFS/DGS/22q11.2 deletion syndrome)." (PMID 24797903, 2014).
DiGeorge syndrome (continued). "Haploinsufficiency of TBX1 in humans is associated with velo-cardio-facial syndrome/DiGeorge syndrome (VCFS/DGS), which causes sensorineural hearing loss in approximately 10% of patients." (PMID 19476657, 2009). "Then, we identified the role of the transcription factor Ripply3 overdosage in midface shortening through the downregulation of Tbx1, another transcription factor involved in the CF midface phenotype encountered in DiGeorge syndrome." (PMID 40982554, 2025). "Tbx1 Is the first dosage-sensitive gene identified in the DiGeorge syndrome (DGS)/velocardiofacial syndrome (VCFS), a congenital disorder characterized by neural-crest-related developmental defects." (PMID 40982554, 2025). "RIPPLY3 was characterized as a transcriptional co-repressor known to be regulating TBX1, a major gene involved in DiGeorge syndrome." (PMID 40003558, 2025). "The duplicated region contained TBX1, which is related to DiGeorge syndrome or Velocardiofacial syndrome." (PMID 39906551, 2024). "Tbx1-knockout mice exhibited skull base and vertebral abnormalities similar to those seen in DiGeorge syndrome." (PMID 38608674, 2024). "The main mutated gene in DiGeorge syndrome is T-box transcription factor 1 (TBX1), which is responsible for provoking the features of DiGeorge syndrome, like hypoparathyroidism, thymic hypoplasia, abnormal facial features, and congenital heart defects." (PMID 38562270, 2024). "For example, the notion that head and neck muscles, together with the heart, are affected in DiGeorge syndrome indicates that they emerge from the Tbx1-expressing CPF." (PMID 37125615, 2023). "The gene TBX1, located on chromosome 22q11.21, has been found in patients with the DiGeorge syndrome." (PMID 38003449, 2023). "A 22q11.21 microdeletion encompassing the TBX1, SHANK3, SOX10, AP1B1, FBXO7, MYH9, and SPECC1L genes cause DiGeorge syndrome, which is associated with DD, ID, seizure, and cardiac malformations, with a prevalence of 1 in 4000." (PMID 37189911, 2023). "The major phenotypes of DiGeorge syndrome can potentially be explained by TBX1 haploinsufficiency, with other symptoms attributed to the cumulative effects from loss of other 22q11.2 genes." (PMID 37125615, 2023). "used heterozygous Tbx1 null mutant mice and demonstrated that haploinsufficiency results in the characteristic cardiopharyngeal phenotype, as seen in 22q11.2 deletion syndrome." (PMID 38205435, 2023). "CDKN1A is a reported target gene in a mouse TBX1 deletion model of the DiGeorge syndrome, highlighting CDKN1A as a general target of TBX1." (PMID 38203204, 2023). "Here we performed single-cell RNA-sequencing of NCCs from the pharyngeal apparatus with the heart in control mouse embryos and when Tbx1, the gene for 22q11.2 deletion syndrome, is inactivated." (PMID 36941249, 2023). "Tbx1 mutant mice are a model of 22q11.2 deletion syndrome (22q11.2DS), a relatively common chromosome microdeletion disorder, for which most of the clinical problems result from TBX1 haploinsufficiency." (PMID 36216515, 2022). "We propose that this TBX1-dependent function is part of the pathogenetic mechanism leading to severe abnormalities of the PhAp in the mouse mutants as well as in DiGeorge syndrome." (PMID 35946435, 2022). "TBX1 is within the most candidate gene-relevant interval in human 22q11.2 deletion syndrome (DiGeorge/velocardiofacial syndrome), and Tbx1-mutant mice show similar phenotypes to those of human 22q11.2, in particular TOF." (PMID 33918884, 2021). "22q11.2 deletion syndrome was traditionally detected as megabase (mb) deletions including TBX1 gene in the region resulting in syndromic features of DGS and VCFS." (PMID 34938854, 2021). "Tbx1, a transcription factor linked to CHDs including TOF and the cardiovascular manifestations of DiGeorge syndrome, is known to regulate Vegfr3 during lymphatic vessel development in mice." (PMID 33067626, 2021).